LAMA3 (laminin subunit alpha 3)
Description:
Binding to cells via a high affinity receptor, laminin is thought to mediate the attachment, migration and organization of cells into tissues during embryonic development by interacting with other extracellular matrix components. Laminin-5 is thought to be involved in (1) cell adhesion via integrin alpha-3/beta-1 in focal adhesion and integrin alpha-6/beta-4 in hemidesmosomes, (2) signal transduction via tyrosine phosphorylation of pp125-FAK and p80, (3) differentiation of keratinocytes.
Synonyms: E170; LAMNA; nicein-150kDa; kalinin-165kDa; BM600-150kDa; epiligrin; BM600; JEB2A; JEB2B; JEB2C; LOCS
Tractability: Antibody: its Gene Ontology location is reachable by antibodies, with high confidence; UniProt places it where antibodies can reach, with medium confidence; UniProt predicts a signal peptide or a membrane-spanning region. PROTAC: ubiquitination databases record sites on it. Other modalities: an approved drug acts on it.
Gene: Protein-coding gene on chromosome 18 (23,689,453 to 23,956,222, forward strand). Ensembl gene ENSG00000053747.
Subcellular location: Secreted, extracellular space, extracellular matrix, basement membrane
Subcellular location (Human Protein Atlas): Endoplasmic reticulum; Predicted to be secreted
Pathways (Reactome):
Extracellular matrix organization: Anchoring fibril formation; Assembly of collagen fibrils and other multimeric structures; Degradation of the extracellular matrix; ECM proteoglycans; Formation of the dystrophin-glycoprotein complex (DGC); Laminin interactions; Non-integrin membrane-ECM interactions
Cell-Cell communication: Type I hemidesmosome assembly
Developmental Biology: Developmental Lineage of Pancreatic Ductal Cells
Disease: Attachment of bacteria to epithelial cells
Signal Transduction: MET activates PTK2 signaling
Gene Ontology:
Molecular function: extracellular matrix structural constituent; structural molecule activity; signaling receptor binding
Biological process: endodermal cell differentiation; epidermis development; nervous system development; signal transduction; cell adhesion; cell-cell adhesion; hemidesmosome assembly; regulation of cell adhesion; regulation of cell migration; regulation of embryonic development
Cellular component: extracellular exosome; extracellular matrix; basement membrane; extracellular region; laminin-5 complex; laminin-5B complex; laminin-6 complex; laminin-7 complex; plasma membrane; synapse; adherens junction; hemidesmosome
Genetic constraint (gnomAD): Loss-of-function variants: 217 observed, 330.98 expected, observed/expected ratio (o/e) 0.66, 90% interval 0.59 to 0.73. The upper end of that interval is the gene's LOEUF score, 0.73, which puts it in group 3 of 6, group 1 being the genes least tolerant of losing a copy. Missense variants: 3,424 observed, 3,876.5 expected, observed/expected ratio (o/e) 0.88, 90% interval 0.86 to 0.91. Synonymous variants: 1,307 observed, 1,450.8 expected, observed/expected ratio (o/e) 0.9, 90% interval 0.86 to 0.94.
Homologues: Orthologues: chimpanzee LAMA3 (99% identical), macaque LAMA3 (96% identical), dog LAMA3 (82% identical), rabbit LAMA3 (82% identical), pig LAMA3 (81% identical), rat Lama3 (78% identical), mouse Lama3 (78% identical), guinea pig LAMA3 (69% identical), tropical clawed frog lama3 (53% identical), zebrafish lama3 (15% identical), zebrafish si:ch211-241e1.3 (13% identical). Paralogues in human: LAMA5 (42% identical), LAMA1 (23% identical), LAMA2 (23% identical), HSPG2 (17% identical), LAMA4 (16% identical), USH2A (15% identical), LAMB2 (12% identical), LAMC1 (12% identical), LAMB1 (12% identical), LAMC3 (12% identical), LAMB4 (11% identical), AGRN (11% identical), and 15 more.
Diseases named in the same sentence as LAMA3 in open-access papers:
LAMA3 is named in the same sentence as 98 diseases in open-access papers, as found by Europe PMC text mining. Sharing a sentence is not in itself a finding about the gene and the disease. The quoted sentences say what the papers report.
junctional epidermolysis bullosa (12 papers, 2006 to 2025). "In one such case, a patient with junctional epidermolysis bullosa was found to have two distinct nonsense mutations in the laminin subunit α-3 gene (LAMA3) that were predicted to cause infant mortality in combination (R943X and R1159X)." (PMID 28323884, 2017). "Similarly, junctional epidermolysis bullosa (JEB) results from mutations in the LAMA3, LAMB3, LAMC2, and COL17A1 genes, which lead to defects in the production of laminin 332, an important protein to help attach the epidermis to the dermis." (PMID 30783081, 2019). "Interestingly, the same stop suppression context in the LAMA3 gene has been shown to alleviate the disease severity of an otherwise fatal nonsense mutation in a patient with junctional epidermolysis bullosa, the major and most devastating form of epidermolysis bullosa." (PMID 25247702, 2014). "Biallelic mutations in LAMA3, LAMB3, and LAMC2 cause junctional epidermolysis bullosa with severe enamel hypoplasia in humans, while single allelic defects in LAMA3 and LAMB3 cause localized enamel defects without skin fragility." (PMID 40362374, 2025). "Recessive dystrophic epidermolysis bullosa (RDEB) and junctional epidermolysis bullosa (JEB) are severe blistering skin disorders caused by mutations in genes encoding type VII collagen (COL7A1) and laminin 332 (LAMA3, LAMB3, or LAMC2), respectively." (PMID 41210582, 2025). "The LAMA3 gene is the responsible gene of Herlitz type junctional epidermolysis bullosa (OMIM #226700), generalized atrophic benign epidermolysis bullosa (OMIM #226650), and laryngo-onycho-cutaneous syndrome (OMIM #245660)." (PMID 35663266, 2022). "Mutations in LAMA3, LAMC2, COL17A1, ITGA6, and ITGB4 are associated with the blistering skin disorder junctional epidermolysis bullosa and cause severe enamel hypoplasia, grooves and enamel pitting." (PMID 31417410, 2019). "Mutations in both alleles of LAMA3, LAMB3, and LAMC2 can cause junctional epidermolysis bullosa (JEB)." (PMID 25769099, 2015). "More recently, CEAs have enabled epithelial gene therapy in patients with junctional epidermolysis bullosa (JEB), a blistering disease in which epithelia are inadequately anchored to the basement membrane owing to mutations in genes encoding laminin 332 (LAMA3, LAMB3, and LAMC2)." (PMID 29288165, 2018). "These same genes, under an autosomal recessive inheritance transmission are responsible for various forms of epidermolysis bullosa (EB: Non-Herlitz junctional epidermolysis bullosa (nH-JEB) COL17A1; recessive dystrophic epidermolysis bullosa (RDEB) COL7A1; junctional EB (JEB) LAMA3, LAMB3, LAMC2)." (PMID 37228816, 2023).
epidermolysis bullosa (11 papers, 2013 to 2024). Epidermolysis bullosa (EB) is a group of genetic skin diseases that cause the skin to blister very easily. "Lau and colleagues demonstrate the prevalence of LAMA3 variants in epidermolysis bullosa (EB) patients with airway disease." (PMID 38429928, 2024). "Previous studies found that targeted disruption of the LAMA3 gene causes junctional epidermolysis bullosa in many animals." (PMID 36674681, 2023). "Loss-of-function mutations in human LAMA3 gene are found in heritable forms of epidermolysis bullosa and Lama3 deletion in mice leads to similar skin blistering pathologies." (PMID 33031376, 2020). "Wang R., Sun L., Habulieti X., Liu J., Guo K., Yang X., Ma D.,Zhang X. Novel variants in LAMA3 and COL7A1 and recurrentvariant in KRT5 underlying epidermolysis bullosa in five Chinesefamilies." (PMID 36923479, 2023). "LAMA3-related diseases include laryngeal cartilage skin syndrome and epidermolysis bullosa, LAMA4-related diseases include cardiomyopathy, while LAMA5-related diseases include peripheral retinal degeneration and nephrotic syndrome." (PMID 32213190, 2020). "The partial deletion of LAMA3 is responsible for epidermolysis bullosa in horses; NAALADL2 is believed to be responsible for immune homeostasis, and TAFA2 (FAM19A2) is believed to be responsible for the regulation of feed intake and metabolic activities in mice." (PMID 34051743, 2021). "Mutations of LAMA3, LAMB3, LAMC2, DST, and COL17A1 have been reported in heritable skin fragility disorders and epidermolysis bullosa (EB)." (PMID 36430582, 2022). "Notably, LAMA3, LAMB3, and ITGB4 are involved in junctional epidermolysis bullosa." (PMID 37745851, 2023).
ovarian carcinoma (11 papers, 2013 to 2025). A malignant neoplasm originating from the surface ovarian epithelium. "LAMA3 and its variants expressions are exacerbated that increase the motility and invasiveness in ovarian cancer." (PMID 33992120, 2021). "The AUC of LAMA3 methylation predicting chemotherapy resistance is 0.67 and 0.71, indicating that the LAMA3 methylation level has a certain diagnostic value for the chemotherapy outcome of ovarian cancer patients." (PMID 33992120, 2021). "Our data further strengthen the findings that low LAMA3 expression is associated with poor prognosis in ovarian cancer, and that this low expression is likely to be regulated by methylation." (PMID 33992120, 2021). "LAMA3 hypermethylation and low expression are both associated with chemotherapy resistance and poor prognosis in ovarian cancer." (PMID 33992120, 2021). "Ovarian cancer patients with low LAMA3 expression are associated with poorer OS and PFS (OS:60.00(95%CI 46.63–73.57) VS 46.00(95%CI 31.51–60.49),P = 0.021; PFS:64.00(95%CI 36.71–91.29) VS 29.00(95%CI 3.97–54.03), P = 0.002)." (PMID 33992120, 2021). "LAMA3 is involved in cell adhesion, signal transduction and differentiation and its mutations were previously reported in brain cancer, ovary cancer and melanoma." (PMID 23301059, 2013). "Similarly, LAMA3 hypermethylation has been linked to chemotherapy resistance and poor prognosis in ovarian cancer, indicating that methylation patterns can serve as potential biomarkers for treatment outcomes." (PMID 41219748, 2025). "However, it should be noted that there is context specificity as high expression of LAMA3 in ovarian cancer was associated with better OS, recurrence-free survival, and 5-year survival rates." (PMID 37779898, 2023). "The hypermethylation of NCALD and LAMA3 in promoters may be the cause of its downregulation in chemoresistance ovarian cancer patients." (PMID 34289901, 2021). "The expression of LAMA3 in ovarian cancer tissues was lower than that in adjacent tissues and normal tissues." (PMID 34289901, 2021). "In chemoresistance ovarian cancer patients, LAMA3 has abnormally high methylation and low expression." (PMID 33992120, 2021). "In this study, we used bioinformatics to predict LAMA3 methylation and confirmed its ability to predict chemotherapy resistance and prognosis of ovarian cancer." (PMID 33992120, 2021). "Although the LAMA3 methylation level predicts chemotherapy resistance in ovarian cancer has certain predictive value, it still needs to be combined with other biomarkers to further improve the predictive efficacy." (PMID 33992120, 2021). "Tang found that the methylation of LAMA3 in ovarian cancer tissues was higher than that in adjacent tissues and normal tissues." (PMID 34289901, 2021). "LAMA3 is a widely studied methylated gene in multiple tumors, but the relationship between chemotherapy resistance in ovarian cancer is unclear." (PMID 33992120, 2021). "After upregulation of LAMA3, the proliferation ability of chemoresistant ovarian cancer cell decreased, while the ability of apoptosis, invasion and migration increased." (PMID 33992120, 2021). "Consistent with findings in other cancers, LAMA3 promotes the invasion and migration of chemoresistant ovarian cancer cell." (PMID 33992120, 2021). "In order to investigate the accuracy of bioinformatics prediction of LAMA3 methylation, we examined the methylation and expression levels of LAMA3 in ovarian cancer patients with chemotherapy outcomes." (PMID 33992120, 2021). "In this study, LAMA3 methylation was predicted by bioinformatics, and the ability of LAMA3 methylation to predict the chemotherapy resistance and prognosis of ovarian cancer was confirmed in experiments." (PMID 33992120, 2021). "Tang found that LAMA3 is abnormally hypermethylated in ovarian cancer, but the relationship between LAMA3 methylation and chemotherapy resistance in ovarian cancer has not been reported." (PMID 33992120, 2021).
ovarian carcinoma (continued). "In the future, the mechanism of LAMA3 methylation in ovarian cancer will need to be further studied." (PMID 33992120, 2021). "Third, LAMA3 overexpression increases the apoptosis, invasion and migration of chemoresistant ovarian cancer cell." (PMID 33992120, 2021). "The AUC of LAMA3 protein expression predicting chemotherapy resistance in ovarian cancer was 0.58 (95% CI 0.489–0.661, P = 0.093)." (PMID 33992120, 2021). "As far as we know, this is the first study to link LAMA3 methylation with chemotherapy resistance and clinical prognosis in ovarian cancer." (PMID 33992120, 2021). "Important new findings include the identification of two new key genes, NCALD and LAMA3, which may drive the acquired resistance of ovarian cancer." (PMID 34289901, 2021). "Our study found for the first time that LAMA3 was abnormally hypermethylated and silenced in chemoresistant ovarian cancer patients, which may be a target gene of epigenetic therapy." (PMID 34289901, 2021). "Invasion and migration experiments showed that the CI value of SKOV3DDP-LAMA3-High was significantly higher than that of SKOV3DDP, indicating that the invasion and migration ability of chemotherapy resistance ovarian cancer cells was significantly enhanced after overexpression of LAMA3." (PMID 33992120, 2021). "However, there is only one study of LAMA3 in ovarian cancer." (PMID 34289901, 2021). "These included LAMA3 mutations (lung squamous) and NOS1 mutations (breast cancer), which were identified as MEK inhibitor-specific biomarkers, and ST18 mutations (lung adenocarcinoma and ovarian cancer), which were identified as HDAC inhibitor-specific biomarkers." (PMID 28561042, 2017). "Although NCALD and LAMA3 are genes that show both methylation and expression changes, the methylation of the ITGB6 gene may also play a role in the chemoresistance of ovarian cancer." (PMID 34289901, 2021). "This shows that NCALD, LAMA3 and ITGB6 may influence each other and participate in the chemotherapy resistance of ovarian cancer together." (PMID 34289901, 2021). "The relationship between LAMA3 and ovarian cancer chemoresistance has not been reported." (PMID 34289901, 2021). "However, the molecular mechanism of LAMA3 in ovarian cancer and its relationship with chemotherapy sensitivity is not clear." (PMID 33992120, 2021).
pancreatic cancer (10 papers, 2019 to 2025). "High LAMA3 expression is strongly associated with cancer invasion and metastasis, particularly in pancreatic cancer." (PMID 40065765, 2025). "Abnormal expression of LAMA3 has been reported in breast, ovarian, gastric, hepatic, and pancreatic cancers, and is associated with tumor aggressiveness." (PMID 41264049, 2025). "The expression of LAMA3 was markedly increased within pancreatic tumour tissues and was linked to the advanced stage and poor prognosis." (PMID 37745080, 2023). "Similarly, DSC2, DSG2, and LAMA3 were also found to be highly expressed and significantly associated with poor prognosis in pancreatic cancer." (PMID 35570408, 2022). "LAMA3 has variable gene expression patterns in different cancer cells, with high expression levels in hepatocellular carcinoma and pancreatic cancer and lower expression levels in gastric, breast, and prostate cancer." (PMID 38877482, 2024). "The expression of LAMA3 and LIPH was markedly increased within pancreatic tumour tissues and was linked to advanced stage and poor prognosis." (PMID 37745080, 2023). "In the present study, we initially screened out four differentially expressed subunits (LAMA3, LAMA4, LAMB3 and LAMC2) of the laminin gene family that were found to be associated with the clinical outcome of pancreas cancer patients in TCGA." (PMID 31182680, 2019). "For the laminin subunits (LAMA3, LAMA4, LAMB3 and LAMC2) that were found to be associated with the prognosis of pancreatic cancer, we further analyzed their TCGA tumor tissue expression profiles." (PMID 31182680, 2019). "High expression of LAMA3 may enhance interactions between pancreatic cancer cells and nerve cells, thereby facilitating tumor dissemination along nerve bundles." (PMID 41264049, 2025). "Moreover, our study reveals the potential mechanism that hsa-miR-15a-5p regulates COL1A2, ITGA2, and LAMA3 so that monocytes and M1 macrophages are activated, which may have great effects on pancreatic cancer prognosis." (PMID 35899199, 2022). "Utilizing GEPIA platform, the mRNA expression of LAMA3 and LIPH between pancreatic tumour and normal tissues was investigated." (PMID 37745080, 2023). "Finally, we used single-cell analysis to further reveal the cell subpopulation composition in pancreatic tumour microenvironment, as well as the relative expression of LIPH and LAMA3 in different cell subpopulations." (PMID 37745080, 2023).
breast carcinoma (7 papers, 2017 to 2023). "In coincidence with our data, a previous study reports that LAMA3 promoter methylation frequency was inversely associated with increased tumour stage and tumour size in breast cancer." (PMID 31703415, 2019). "Accordingly, the role of JAK2 and LAMA3 in HER2+ breast cancer cells and their modulation by PGB-0-ol should be investigated further." (PMID 38028209, 2023). "High methylation and low expression of LAMA3 are found in breast cancer, lung cancer, bladder cancer and other malignant tumors." (PMID 33992120, 2021). "The promoter of LAMA3 is methylated in breast carcinoma, and the frequency of methylation is associated with tumor stage and tumor size, indicating that LAMA3 upregulation might have a tumor‐suppressive role in breast cancer." (PMID 34981672, 2022).
pancreatic ductal adenocarcinoma (7 papers, 2020 to 2025). An infiltrating adenocarcinoma that arises from the epithelial cells of the pancreas. "LAMA3 encodes laminin subunit alpha-3, which plays a vital role in growth by interacting with other components of the extracellular matrix and mediates cell proliferation, migration, and invasion in pancreatic ductal adenocarcinoma cells." (PMID 38028209, 2023). "Increased level of LAMA3 was reported in pancreatic ductal adenocarcinoma, ovarian and liver cancer." (PMID 34366863, 2021).
lung adenocarcinoma (6 papers, 2017 to 2025). A carcinoma that arises from the lung and is characterized by the presence of malignant glandular epithelial cells. "Additionally, studies have illuminated the epigenetic interaction of LINC00628 with the LAMA3 promoter, culminating in the development of lung adenocarcinoma." (PMID 37965447, 2023).
head and neck cancer (5 papers, 2009 to 2020). A primary or metastatic malignant neoplasm affecting the head and neck. "The impact of hypoxia on post-transcriptional events is proven also by LAMA3-A (Laminin alpha 3), a splicing variant of the LAMA3 gene induced by reduction of oxygen supply which promotes cell invasion and is associated with a poor prognosis in head and neck cancer." (PMID 24285959, 2013). "Consistent with a positive role in tumor progression, expression of the short LAMA3 isoforms, which is multiply controlled by the transcriptional co-activator EP300, along with the transcription factors AP-1, CREB1 and USF1, is increased and portends a dismal prognosis in head and neck cancers." (PMID 24324612, 2013).